ERG (ETS transcription factor ERG)
Diseases named in the same sentence as ERG in open-access papers (continued):
Sharing a sentence is not in itself a finding about the gene and the disease.
prostate carcinoma (continued). "In contrast to our observations in prostate cancer (r2 = 0.84), ERG and TDRD1 were not co-expressed in CA-AML (r2 = 0.07)." (PMID 23555854, 2013). "The availability of ERG data from a previous study made it possible to search for associations between ERG and p27, and compare p27 scores and prostate cancer phenotypes, in separate subsets of ERG fusion-positive and -negative cancers." (PMID 24179503, 2013). "Gene expression measurements by real-time quantitative PCR revealed a remarkable co-expression of TDRD1 and ERG (r2 = 0.77) but not ETV1 (r2<0.01) in human prostate cancer in vivo." (PMID 23555854, 2013). "The formation of the TMPRSS2-ERG gene fusion that occurs in about 50% of prostate cancers has been shown to be facilitated by androgen signaling which induces proximity of the TMPRSS2 and ERG genomic loci and then exposure to gamma irradiation which causes DNA double-strand breaks." (PMID 24261984, 2013). "Accordingly, overexpression of TDRD1 in ERG-negative LNCaP cells did not lead to changes in cell viability (data not shown), suggesting that expression of TDRD1 is not required for proliferation of ERG-rearranged prostate cancer cells in vitro." (PMID 23555854, 2013). "Because of the controversial prognostic utility of TMPRSS2:ERG fusion in prostate cancer, we employed the strategy of a three-marker FISH panel to detect well documented prostate cancer DNA aberrations, including TMPRSS2/ERG rearrangements, AR copy number gain, and PTEN deletion." (PMID 24098661, 2013). "Our study demonstrates high-level MTC02 expression in ERG negative prostate cancers harboring deletions of PTEN, 6q15, and 5q21." (PMID 24261794, 2013). "Our approach included comparison of prostate cancer versus benign prostate tissue, and ERG rearrangement-positive (ERG+) to ERG rearrangement-negative (ERG−) prostate cancers." (PMID 23390522, 2013). "We focused on a comparison of ERG+ and ERG− prostate cancers because these subtypes were described recently and have not been extensively investigated so far." (PMID 23390522, 2013). "Analysis of the prostate cancer transcriptome performed by us and others demonstrated that tumors harboring the TMPRSS2:ERG fusion share a unique gene expression profile which significantly differs from profiles of benign prostate tissue and malignant tumors lacking the fusion." (PMID 23555854, 2013). "Our study indicates that these proteins possibly present ERG+ prostate cancer rather than general prostate cancer markers." (PMID 23390522, 2013). "No information was available concerning the ERG rearrangement status of the prostate cancer samples used in the studies of the meta-analysis." (PMID 23390522, 2013). "Accordingly, demethylation of the TDRD1 promoter in TMPRSS2:ERG-negative prostate cancer cells by DNA methyltransferase inhibitors resulted in TDRD1 induction." (PMID 23555854, 2013). "It is well established that ERG expression is not entirely specific to ERG-rearranged prostate cancer cells: ERG is known to be expressed in endothelial cells and in the hematopoietic lineage." (PMID 23555854, 2013). "In contrast to prostate cancer, there was no co-expression of ERG and TDRD1 in any of these studies (r2 = 0.03 and 0.02, respectively)." (PMID 23555854, 2013). "Androgen induces prostate cancer-specific translocations of TMPRSS2: ERG in prostate cancer cells but not in non-malignant prostate epithelial cells." (PMID 23272087, 2012). "Although the gene signatures of all forms of urogenital cancer/diseases are largely unknown, the six known prostate cancer genes of AGR2, AMACR, CRISP3, ERG, HPN, and PCA3 are at or below background, for example, in bladder cancer." (PMID 23029164, 2012). "The samples were classified as 352 ERG fusion-negative prostate cancer samples (ERG0) and 103 ERG fusion positive prostate cancer samples (ERG1)." (PMID 22811706, 2012).
prostate carcinoma (continued). "Using a histogram format for data display, all signal counts for the selected prostate cancer genes were at background for P08-022N: AGR2 = 0.08 [(8 counts, relative to B2M = 100 (10,000 counts)], AMACR = 0.46, CD90v = 0.02, CRISP3 = 0.25, ERG = 0.1, HPN = 0.04, PCA3 = 0.09 (data entries in blue)." (PMID 23029164, 2012). "These prostate cancer-specific gene rearrangements may be explained by the fact that androgen treatment in AR-positive prostate cancer cell lines induced proximity between TMPRSS2 and ERG." (PMID 22110995, 2011). "Since ERG and ETV1 belong to the same class of ETS factors as FLI1, we tested the ability of YK-4-279 to inhibit biological functions of ERG and ETV1 proteins in prostate cancer." (PMID 21559405, 2011). "The DNA binding domain of ERG shares 98% homology with that of FLI1 and our own unpublished results suggest that there is significant overlap between EWS-FLI1 target genes in ESFT and ERG in prostate cancer cells." (PMID 22135504, 2011). "The majority of ERG-positive prostate cancer samples had reduced or absent PTEN expression, suggesting that ERG rearrangements and loss of PTEN were concurrent genetic events." (PMID 22110995, 2011). "Although activity of miR-145 on EWS-ERG in ESFT remains to be demonstrated, the finding of ERG modulation by this miRNA in prostate cancer cells may extend the concept of feedback regulation between EWS-ETS fusion genes and miR-145 beyond EWS-FLI1." (PMID 22135504, 2011). "The anti-migratory effect was not restricted to ERG positive prostate cancer cells supporting the rationale of PLA2G7 inhibition in the prevention and treatment of aggressive and metastatic tumors." (PMID 22202492, 2011). "Among the genes significantly affected by all three ERG fusions, we noted the up-regulation of PIM1, an oncogene whose expression is increased in tumors from both haematological and epithelial origin, including prostate cancer." (PMID 22140532, 2011). "In these experiments we over-expressed ERG in ERG-translocation negative 22Rv1 and LNCaP prostate cancer cells that do not express endogenous ERG." (PMID 20479932, 2010). "We compared prostate cancer with Burkitt's lymphoma because both harbor a recurrent translocation that leads to the over expression of two known oncogenes: c-MYC for Burkitt's lymphoma and ERG for prostate cancer." (PMID 20233430, 2010). "In contrast, the Nkx3.1 promoter was methylated in ERG-translocation negative PC3 prostate cancer cells that do not express Nkx3.1 indicating that in these cells Nkx3.1 was silenced by CpG promoter methylation." (PMID 20479932, 2010). "Prostate cancer up-regulation has been previously documented for ATF3, RUNX2 and ERG." (PMID 20021671, 2009). "Using a novel and powerful bioinformatic technique, they first determined that either ETV1 or ERG (but not both) was commonly overexpressed in prostate cancer cells." (PMID 18781147, 2008). "Tomlins and colleagues (2005) identified recurrent gene fusions of TMPRSS2 to two ETS transcription factors, ERG and ETV1, and found evidence to suggest that these fusions may occur in the majority of prostate cancer cases." (PMID 18694509, 2008). "However, neither ERG nor AR possess clustered promoter binding sites in the promoter of the MCOLN2 gene and, therefore, MCOLN2 up-regulation in prostate cancers with ERG over-expression is not directly performed by these transcription factors." (PMID 40332161, 2025). "We, and others, have identified both specific and shared downstream targets of ERG and ETV1 in prostate carcinomas, supporting the existence of targetable molecular pathways that may overcome the challenges in direct targeting ETS transcription factors as a therapeutic approach." (PMID 40808640, 2025).
prostate carcinoma (continued). "The promoter of TRPM4 that is functional in prostate tissues and prostate cancer did not possess clustered binding sites for ERG, AR, TCF4 or Slug but did have multiple binding sites for SMAD transcription factors, suggesting dominant regulation by the TGFβ pathway." (PMID 40332161, 2025). "Although other ETS family members such as ERG comprise recurrent oncogenic gene rearrangements in prostate carcinoma, we did not identify a pattern of expression of other ETS genes that could substitute for the loss of ETV1 function across LNCaP strains." (PMID 40956611, 2025). "Recurrent gene fusions between TMPRSS2 (transmembrane protease serine 2) and the gene ERG, a member of the transcription factor erythroblastosis virus E26 transforming sequence family (ETS), are highly specific to PCa and can be found in up to 40-50% of prostate carcinomas." (PMID 39083067, 2024). "In this review, we discuss the involvement of key TFs, including the E26 Transformation-Specific (ETS) Family (ERG and SPDEF), NF-κB, Activating Protein-1 (AP-1), MYC, and androgen receptor (AR), in prostate cancer while focusing on the molecular mechanisms involved in prostate cancer development." (PMID 38674385, 2024). "However, arguing against this indirect model, other immunohistochemical analyses have shown that higher levels of ESRP1 protein correlate with a shorter time to prostate cancer biochemical recurrence independent of ERG translocation status." (PMID 37752235, 2023). "For the endothelium, although a few prostate cancer cases with ERG rearrangement could be positive in ERG staining, we confirmed that the prostate cancer cases in our cohort were negative in ERG staining." (PMID 36873900, 2023). "Prostate cancer prognosis and mechanisms are not solely dependent on ERG expression." (PMID 37509339, 2023). "The fusion of the androgen-regulated serine protease TMPRSS2 with the ETS family transcription factor ERG along with the inactivating rearrangements of the tumor suppressor gene phosphatase and tensin homolog (PTEN) are among the most common genetic alterations in prostate cancer." (PMID 37185705, 2023). "However, the prognostic value of aberrations in ERG and other ETS genes is still inconclusive, which is best explained by the lack of sufficiently large studies accounting for the common multifocality and heterogeneity of prostate cancer." (PMID 35574900, 2022). "Moreover, SOX4 was shown to interact with ERG itself and promote EMT in prostate cancer cells." (PMID 34708244, 2022). "Currently, there is no ERG-targeted therapy approved for treatment of prostate cancer." (PMID 35513774, 2022). "Our preliminary reporter gene analysis demonstrated that NOS3 could not be directly transactivated by ERG in prostate cancer cells." (PMID 35526071, 2022). "In ~50% of prostate cancers a chromosomal rearrangement results in the fusion of the androgen-regulated promoter of TMPRSS2 to the open reading frame of ERG and results in aberrant expression of either full-length, or N-terminally truncated ERG protein in prostate epithelium." (PMID 34314419, 2021). "ETS-related gene (ERG) upregulates the downstream mediator transcription factor of the Wnt/β-catenin signaling pathway named Lymphoid enhancer-binding factor 1 (LEF1), which in turn enhances the androgen receptor expression and activity, leading to prostate cancer in an androgen-independent manner." (PMID 35201496, 2021). "In a nutshell, in our belief, evaluation of ERG expression and its intensity may have no essential role as an acceptable prognostic factor for anticipating whether prostate cancer itself or the outcomes accompanied in Iranian population." (PMID 34567190, 2021). "Four different multivariate analyses were applied to evaluate whether ESRP1 or ESRP2 expression as well as our ESRP1/ESRP2 score is a statistically independent prognostic marker in all prostate cancers and the subset of ERG-negative and ERG-positive cancers." (PMID 33339518, 2020).
prostate carcinoma (continued). "In prostate cancers, 40-80% of tumors harbor a gene fusion between the androgen receptor (AR)-responsive transmembrane protease serine 2 (TMPRSS2) gene and E26 transformation-specific (ETS) family transcription factor, most often the oncogene ETS-related gene (ERG)." (PMID 33135109, 2020). "Vainio et al196 observed that PLA2G7 overexpression was present in a majority of clinical prostate tumors and correlated positively (r = 0.66, P < .001) with the expression of ERG, an E twenty‐six gene (ETS)‐related gene that may be involved in the initiation and progression of prostate cancer." (PMID 31140638, 2020). "TMPRSS2-ERG or any ERG fusions were absent among African prostate cancers." (PMID 31366128, 2019). "For instance, TMPRSS2 interacts with ERG and PTEN (see the example above) in the STRING version 10 protein-protein interaction (PPI) network; in fact all 3 genes co-operate to modulate the NOTCH signaling pathway in TMPRSS2-ERG–positive prostate cancer progression." (PMID 30978274, 2019). "Likewise, in subsets of prostate cancer patients with ERG fusion negative, increased expression of PHH3 and Ki-67 or PTEN deletion, are associated with increased risk of lethal progression." (PMID 31741711, 2019). "Our results did not rule out the possibility that prostate cancer subtypes with alteration in ERG and MYC may exist in NEPC, without an involvement of TNC through alternative pathways." (PMID 31798767, 2019). "Indeed, ERG is one of the most overexpressed oncogenes in prostate cancer, where a chromosomal translocation results in the fusion of the promoter region of androgen-regulated transmembrane protease serine 2 (TMPRSS2) with the DNA-binding domain of ERG." (PMID 31817884, 2019). "This may activate different pathways and hormonal interactions compared with ERG fusion-negative prostate cancer leading to differential interactions with FOXP2 and distinctive tumor progression." (PMID 29725501, 2018). "In order to demonstrate whether the T:E fusion could be regulated by ERRα, we examined the effects of suppression of ERRα activity or its overexpression in two prostate cancer cell lines, VCaP and NCI-H660, both harbor the T:E fusion gene and express T:E transcripts and ERG protein." (PMID 30042415, 2018). "In addition to confirm several previous studies, we found novel recurrent SCNA for ERG-negative prostate cancers, such as ZNF292 deletion." (PMID 30150711, 2018). "It is well known that about the half of prostate cancers carry a gene fusion, which links the androgen-regulated serine protease TMPRSS2 with the ETS-transcription factor ERG resulting in an androgen-related expression of ERG with subsequent dysregulation of more than 1600 ERG target genes." (PMID 29304771, 2018). "Therefore, identification of driver events in ERG-negative prostate cancer is important for understanding the mechanism of tumorigenesis." (PMID 30150711, 2018). "Our study provides new insights into the molecular landscape of ERG-negative prostate cancers." (PMID 30150711, 2018). "Altogether, the genomic and molecular characteristics revealed in our study may provide new opportunities for molecular stratification of ERG-negative prostate cancers." (PMID 30150711, 2018). "Detection of nuclear YB-1 may have clinical value to identify a subgroup of patients with aggressive ERG-negative prostate cancers." (PMID 28515422, 2017). "Given its statistical independence of established prognostic features, it cannot be excluded, that GGH expression measurement may aid in decision-making in ERG-negative prostate cancers if combined with other markers." (PMID 28146062, 2017). "Whether a VDR agonist can reduce the growth of a prostate cancer cell line containing a TMPRSS2:ERG rearrangement in vivo has not been resolved." (PMID 28591703, 2017).
prostate carcinoma (continued). "A recent study revealed ERG-specific metabolic alterations, particularly connected to fatty acid oxidation and an earlier study found increased glucose uptake to be related to the metabolic sensor neuropeptide gamma (NPY) in ERG rearrangement positive prostate cancer." (PMID 27276682, 2016). "The data of this study suggest that pure “fusion-type” prostate cancer, where TMPRSS2:ERG fusions constitute a potential initiating event, may occur in not more than one third of all prostate cancer foci." (PMID 27530104, 2016). "How the fusion products regulate prostate cancer remains unclear, although it has been observed that an increased incidence of the TMPRSS2:ERG fusion protein in prostate epithelial cells correlates with increased cell invasiveness, poor prognosis and higher rates of malignancy." (PMID 27208692, 2016). "Using the expression data of our series of prostate carcinomas subtyped for ETS rearrangements, we show that both PC3 and MDA-PCa-2b cells have co-overexpression of ETV1 and ETV4, both ETS in higher levels than those of ERG in VCaP cells, the in vitro model of the TMPRSS2-ERG rearrangement." (PMID 25595908, 2015). "Of these, overexpression of the ETS-related gene (ERG), resulting from the fusion of ERG coding sequences to the androgen-responsive TMPRSS2 gene, represents the most common subtype, with a prevalence of approximately 50% in clinically localized prostate cancers." (PMID 25889691, 2015). "However, by themselves, neither ERG nor SPINK1 appear to be useful biomarkers for prognostication of early stage prostate cancer." (PMID 26172920, 2015). "Therefore, there might be possible roles for assessment of ERG and SPINK1 expression in prostate cancer care in the future." (PMID 26172920, 2015). "Moreover, SENP1 overexpression has strong prognostic value in the subset of ERG-positive prostate cancers lacking PTEN deletions." (PMID 26202067, 2015). "Despite the fact that mutual exclusivity of ETS rearrangements is the rule (at least at the cellular level) in prostate carcinomas and the impact on cell invasion shared by ERG and ETV1, ETS members show both lack of tissue specificity and co-expression within a tissue." (PMID 25595908, 2015). "Additionally, SPINK1 overexpression has a tight correlation with small deletions of 6q15- and 5q21 in ERG negative prostate cancers." (PMID 24739220, 2014). "The tight link between CRISP3 expression, ERG gene rearrangements and/ or PTEN deletions in the three cohorts of prostate cancer studied, suggest the presence of distinct molecular alterations in this subgroup of tumors that may have additional clinical implication if assessed collectively." (PMID 24606912, 2014). "Of these, overexpression of the ETS-related gene (ERG), resulting from the fusion of ERG coding sequences to the androgen-responsive TMPRSS2 gene, represents the most common subtype among ETS fusions, with a prevalence of approximately 50% in clinically localized prostate cancers." (PMID 25221645, 2014). "We also aimed to validate the prognostic value of CRISP3 in conjunction to the molecular subtype of PCA with ERG and PTEN genomic aberrations and to utilize bioinformatics to delineate possible genetic connections and pathways related to this molecular subtype of prostate cancer." (PMID 24606912, 2014). "The intriguing observation that altered ERG expression can significantly affect C-MYC levels in the VCaP cells prompted us to re-examine Type I/Type II ratios and C- MYC expression from our previously published qRT-PCR data from laser capture micro- dissected (LCM) prostate cancer cells." (PMID 25221645, 2014). "VCaP are a human androgen-dependent prostate cancer cell line derived from a vertebral metastasis that harbors similar characteristics to human prostate cancer specimens including wild-type PTEN status (seen in approximately 50% of prostate cancers) and expression of the TMPRSS:ERG fusion gene." (PMID 25344862, 2014).